VCAM1 (vascular cell adhesion molecule 1)
Diseases named in the same sentence as VCAM1 in open-access papers (continued):
Sharing a sentence is not in itself a finding about the gene and the disease.
cardiovascular disease (continued). "Among these molecules, vascular cell adhesion molecule-1 (VCAM-1) plays important roles in the embryonic development of the cardiovascular system and in cardiovascular diseases." (PMID 34803741, 2021). "Enhanced expression of adhesion molecules (such as vascular cell adhesion protein 1, or VCAM‐1) on the endothelial and smooth muscle cell surfaces is associated with cardiovascular disorders in RA and SLE." (PMID 34075600, 2021). "Vascular cell adhesion protein 1 level (VCAM-1) represents a marker of cardiovascular diseases since it is rapidly expressed in pro-atherosclerotic conditions." (PMID 31941075, 2020). "By collecting these data, we have demonstrated a role for VCAM-1 in cell adhesion and that possible damage induced by mononuclear cells in cardiovascular diseases can be reduced by SCFA." (PMID 29615908, 2018). "Soluble vascular cell adhesion molecule 1 (sVCAM-1), P-selectin (sP-selectin) are proposed as biomarkers of cardiovascular disease." (PMID 28646244, 2017). "This agrees with the major proportion of cardiovascular disease and carotid plaques observed in our patients in the highest VCAM-1 tertile." (PMID 26066045, 2015). "Cardiovascular diseases are characterized by overexpression of inflammatory genes and infiltration of the inflammatory cells via adhesion molecule induction such as VCAM-1." (PMID 26858641, 2015). "The infiltration of immune cells is due to up-regulation of adhesion molecules such as VCAM-1, which contributes to chronic inflammatory diseases including cardiovascular diseases." (PMID 26858641, 2015). "The infiltration of immune cells is due to up-regulation of adhesion molecules including ICAM-1 and VCAM-1 which contribute to several chronic inflammatory diseases including cardiovascular diseases." (PMID 26173590, 2015). "Decreased methylation has also been shown to be associated with increased vascular cell adhesion molecule-1 (VCAM-1), a biomarker of vascular inflammation, which suggests a potential functionality of DNA methylation in cardiovascular disease." (PMID 25512264, 2014). "The circulating levels of adhesion molecules like vascular cell adhesion molecule-1 (VCAM-1), intercellular adhesion molecule-1 (ICAM-1) and E-selectin are also associated with inflammation and cardiovascular diseases." (PMID 24376824, 2013). "A direct correlation was found between subjects categorized at higher risk for cardiovascular disease based upon serum triglycerides and postprandial production of TGRL particles that increased VCAM-1-dependent monocyte adhesion to inflamed endothelium." (PMID 24205197, 2013). "Moreover, the cardiovascular disease-related risk factors, including ACE2, VCAM-1, and ICAM-1, were significantly higher in patients with PLWH." (PMID 39669584, 2024). "At the same time, another meta-analysis of randomized clinical trials aimed to determine the effect of statins on serum levels of TNF-α, MCP-1, VCAM1 and IL-6 in patients with cardiovascular diseases showed that statins have a beneficial effect on reducing the serum levels of TNF-α." (PMID 38572445, 2024). "This intricate interplay underscores the pivotal roles of ICAM-1 and VCAM-1 in cardiovascular pathophysiology and accentuates their potential as therapeutic targets for mitigating cardiovascular disease progression, particularly through the modulation of NF-kB signaling." (PMID 39513877, 2024). "Furthermore, Va-CLs-based delivery platforms appear to be potential novel nanocarriers for RNA delivery to VCAM-1 overexpression sites, providing new options for miRNA delivery and cardiovascular disease treatment." (PMID 37242620, 2023). "Since VCAM-1 is mainly involved in the development of vascular inflammation, it has the advantage of being a specific target of vascular inflammation in cardiovascular diseases, thus offering the possibility of designing endothelial inflammation targeted delivery systems." (PMID 37242620, 2023).
cardiovascular disease (continued). "Moreover, the interplay between TNF-α and VCAM-1 plays an important part in cardiovascular disorders." (PMID 35281466, 2022). "Previous studies have confirmed that vascular endothelial inflammatory factors IL-1β, TNF-α, and adhesion factors ICAM-1 and VCAM-1 are essential markers of vascular endothelial injury and dysfunction, which can predict cardiovascular disease, and correlate with the severity of ACS." (PMID 35302437, 2022). "Knockdown of VCAM1 or blockade of integrin α4β1 with antibodies has been reported to reduce neointima formation in the carotid artery of rodents, indicating the important role of VCAM1 in cardiovascular diseases." (PMID 30388809, 2018). "The induction of endothelial VCAM1 in vitro may explain the context-specific role of miR-19a in cardiovascular diseases." (PMID 29477147, 2018). "In accordance with the participation of VCAM-1 in the alteration of the heart and vascular function, increased levels of this molecule have been correlated with the development of cardiovascular diseases in healthy middle-aged men during a 6.6 years follow-up study." (PMID 29416512, 2018). "Interestingly, when vascular VCAM-1 protein levels were divided into tertiles, age, c-IMT measurements, as well as a major proportion of cardiovascular disease and carotid plaques disease were significantly increased in the highest VCAM-1 tertile." (PMID 26066045, 2015). "Although the relationship between the degree of cellular ICAM-1 and VCAM-1 expression and plasma concentrations of soluble forms is not entirely clear, multiple studies have shown that sICAM-1 and sVCAM-1 predict risk of cardiovascular disease." (PMID 21349799, 2011). "Increased expression of VCAM-1 and ICAM-1 has been shown in SLE tissues such as the skin and heart and high levels of VCAM-1, associated with enhanced systemic TNF-α activity, was recently demonstrated to characterize SLE patients with manifest cardiovascular disease." (PMID 19997561, 2009). "Overall, these results suggested that the LPC-G2A-ICAM-1/VCAM-1 pathway may contribute to the atherogenic activity of oxLDL, with NF-κB antagonists representing potentially viable therapeutic tools for the treatment of cardiovascular disease." (PMID 34346841, 2021). "As expected, among the cardiovascular disease related genes, MMP9, TNF, IFN-ɣ, and VCAM1 genes were the top up-regulated genes in ILC1s was earlier shown to play an important role in the occurrence of post-PCI restenosis." (PMID 32198366, 2020). "Soluble VCAM-1 and ICAM-1, adhesion molecules shed by activated endothelial cells, are considered biomarkers of cardiovascular disease." (PMID 23724003, 2013). "In cardiovascular disease, IL-38 inhibits inflammation and calcium deposition in aortic valve interstitial cells by inhibiting caspase-1, IL-1, intercellular adhesion molecule-1 (ICAM-1), and vascular cell adhesion molecule-1 (VCAM-1)." (PMID 41596472, 2026). "Notable, in the Dallas Heart Study (involving 2,442 participants without prior cardiovascular disease) only soluble ESAM, but not soluble ICAM-1 or soluble VCAM-1, levels were associated with incidents of atherosclerotic and total cardiovascular disease." (PMID 39740345, 2025). "Notable, in the Dallas Heart Study, involving 2442 participants without prior cardiovascular disease soluble ESAM, but not soluble ICAM‐1 or soluble VCAM‐1, levels were associated with incident atherosclerotic and total cardiovascular disease." (PMID 36946064, 2023). "Interestingly, although KLF2 is known to suppress VCAM-1 and ICAM-1 expression under physiological conditions, we observed increased VCAM-1 mRNA expression, consistent with a proinflammatory endothelial phenotype commonly observed in cardiovascular disease." (PMID 41562845, 2026).
cardiovascular disease (continued). "Additionally, vascular cell adhesion molecule 1 (VCAM-1) and oxidized LDL concentrations, markers of cardiovascular diseases, are increased with high-AGE diets in hyperglycemic conditions, which might underpin a positive role of AGE-restricted diets." (PMID 37446161, 2023). "In our study, by inputting hsa-miR-200c-3p, IL-7, VCAM-1 and VEGF-C into the IPA analysis together with glucose to simulate the diabetic state, we predicted that downregulated miR-200c may lead to cardiovascular disease through VEGF signaling and PI3K/Akt signaling pathways." (PMID 36555301, 2022). "VCAM-1 and ICAM-1 are two important members of the immunoglobulin gene superfamily of adhesion molecules, and their potential role as biomarkers of diagnosis, severity and prognosis of cardiovascular disease has been investigated in a number of clinical studies." (PMID 25784313, 2015).
inflammation (87 papers, 2010 to 2025). Aberrant reaction of the microcirculation characterized by movement of fluid and leukocytes from the blood into extravascular tissues. "Concurrently, the endothelium and surrounding glia show heightened expression of immune- and inflammation-related genes, particularly in the white matter Consistent with endothelial inflammation, we find that VCAM1 expression and pericyte loss are most prominent in layer 6/CC." (PMID 40796665, 2025). "To further explore the possible protective mechanism underlying the activity of galangin in airway inflammation, we investigated the expression of VCAM-1, one of the adhesion molecules related to infiltration of inflammatory cells in lungs of OVA-challenged mice." (PMID 23762160, 2013). "Vascular cell adhesion molecule-1 (VCAM-1), a marker of vascular inflammation, has been found to be associated with WMHs in CSVD patients." (PMID 41000387, 2025). "The main findings of the present study suggested that high glucose, via augmenting PTP1B levels, induced p65 phosphorylation and VCAM-1 expression, thus participating in endothelial inflammation." (PMID 35607953, 2022). "It should be noted that miR-126 also regulates endothelial cell adhesion and vascular inflammation by decreasing the adhesion of leukocytes to endothelial cells by binding to VCAM-1." (PMID 35596173, 2022). "IRF1 and REL, a member of the NF-κB family, are key mediators of VCAM1 expression during endothelial inflammation." (PMID 35406678, 2022). "We already confirmed that intraperitoneal injection of TNF-α induced vascular inflammation, such as macrophage infiltration and abnormal mRNA expression of VCAM-1 and inflammatory cytokines such as IL-6 and TNF-α in the mouse aorta." (PMID 34679642, 2021). "Previous research has shown that IL-6, IL-1β, MCP-1, NF-κB, TNF-α, ICAM-1 and VCAM-1 are all involved in the process of vascular inflammation." (PMID 34830730, 2021). "To further illuminate the mechanisms that underlie the impact of TNF-α on lung inflammation/injury, we also examined and found mir-331-3p suppressed the expression of inflammation-associated genes MCP-1, VCAM-1, and ICAM-1 in vitro and in vivo." (PMID 33072088, 2020). "The presence of neopterin in gingival crevicular fluid (GCF) is a marker for local and acute immune activation, and the presence of vascular cell adhesion molecule (VCAM-1) in GCF is accepted as a marker for chronic vascular inflammation." (PMID 29641752, 2018). "Apart from Spred-1, PIK3R2 andEGFL7, miR-126 targets vascular cell adhesion protein 1(VCAM-1), thereby affects the regulation of the adhesionof leukocytes to the endothelium defining anotherrole for miR-126 in vascular inflammation." (PMID 29633591, 2018). "MAPK signaling has been implicated in the transcription of various proinflammatory cytokines (e.g., eotaxin-1, MCP-1, and IL-8) and adhesion molecules (e.g., ICAM-1 and VCAM-1), which contribute to a worsened airway inflammation." (PMID 26783416, 2016). "Rh-APC attenuated pulmonary inflammation, decreased VCAM-1 upregulation and prevented changes in histopathology.Effects on systemic coagulation or systemic bleeding were not reported." (PMID 22546487, 2012). "We have developed a range of novel ligand-conjugated MPIO for molecular MRI of endothelial adhesion molecules, such as vascular cell adhesion molecule-1 (VCAM-1) and P-selectin expressed in vascular inflammation, as well as activated platelet thrombosis." (PMID 19883911, 2010). "Peripheral monocytes attach to the damaged brain ECs expressing intercellular adhesion molecule-1 (ICAM-1) and vascular cell adhesion molecule-1 (VCAM-1), which are the downstream factors of the kappa-light-chain-enhancer of activated B cells (NF-κB) observed during acute CNS inflammation." (PMID 34445248, 2021).
inflammation (continued). "In this respect, increased expression of vascular cell adhesion molecule 1 (VCAM-1) by cholangiocytes contributes to the persistence of liver inflammation through the recruitment of monocytes and lymphocytes, and mediating leukocyte adhesion by binding α4β1 integrins." (PMID 32587513, 2020). "Acute vascular inflammation was induced in the rabbits by placing a silastic collar around the left carotid artery for 24 hours, the carotid collar significantly increased the endothelial expression of VCAM-1 and ICAM-1." (PMID 30327711, 2018). "Adiponectin may also inhibit endothelial inflammation and correlates negatively with vascular inflammation markers such as VCAM-1 and ICAM-I." (PMID 28068986, 2017). "For these reasons, VCAM-1 is an attractive molecular imaging target of acute vascular inflammation." (PMID 19883911, 2010). "Future studies investigating how EV biogenesis-associated markers are altered following endothelial cell activation and on VCAM-1+ EC-EV sub-population may reveal distinct roles of VCAM-1+ EVs in vascular inflammation and in a range of pathologies with vascular dysfunction." (PMID 39698414, 2024). "However, this increase in adhesion was markedly inhibited by the depletion of YAP/TAZ using siRNA in endothelial cells, suggesting that YAP/TAZ is critically involved in endothelial inflammation by regulating the expression of the adhesion molecule VCAM1 and ICAM1." (PMID 30388809, 2018). "In addition, excessive intake of cholesterol may cause vascular inflammation, and pro-inflammatory cytokines such as TNF-α and IL-6 may stimulate the expression of adhesion molecules and chemokines such as VCAM-1, ICAM-1, and fibronectin in aorta tissue." (PMID 24364887, 2013). "Elevated levels of E-selectin, ICAM-1, VCAM-1, and serpin E1 (PAI-1) are indicative of endothelial inflammation and injury." (PMID 38600563, 2024). "miR-520b-3p was shown to suppress endothelial inflammation and block the cross-talk between monocytes and endothelial cells by down-regulating NF-κB p65-ICAM1/VCAM1 axis." (PMID 35071356, 2021). "During vascular inflammation, the expression of adhesion molecules, including ICAM-1, VCAM-1, and E-selectin, is elevated, promoting leukocyte recruitment to the endothelium." (PMID 34925018, 2021). "Subsequently, the expression of molecules crucial for the development of vascular inflammation, including IL-6, MMP-2, MMP-9, VCAM-1, and ICAM-1, was measured." (PMID 34336088, 2021). "Inflammatory factors such as ICAM-1, VCAM-1, TNFα, IL-6, and CRP have key roles in mediating vascular inflammation and blocking RAAS negatively modulates the levels of these inflammatory molecules." (PMID 24804145, 2014). "In the context of intestinal inflammation, mucosal microvascular endothelial cells overexpress cell adhesion molecules (CAMs) including P-selectin, ICAM1, and VCAM1 on both sides of the canal lumen to recruit leukocytes, which trigger a more severe inflammatory response." (PMID 37287987, 2023). "eNAMPT is also involved in vascular inflammation by increasing the expression of endothelial cell adhesion molecules (intercellular adhesion molecule 1 [ICAM-1] and vascular cell adhesion molecule 1 [VCAM-1]) in endothelial cells, which boost the adhesion of monocytes." (PMID 37915565, 2023). "VCAM-1 and ICAM-1 are related to the pathophysiological process of vascular inflammation." (PMID 35620579, 2022). "We found that Aff3ir-ORF2 deletion increased Vcam1 expression in the aortic roots of Apoe-/- mice, indicating that the atherogenic effects of Aff3ir-ORF2 deletion may result from endothelial inflammation." (PMID 40315012, 2025). "Furthermore, we showed that inhibition of TNF‐α significantly reduces the inflammatory responses in cerebral ECs, evidenced by attenuated activation of NF‐κB p65 and expression of VCAM‐1, highlighting a critical role of TNF‐α in reperfusion‐induced endothelial inflammation." (PMID 37789643, 2024).
inflammation (continued). "However, VLA-4 integrin represents an alternative pathway for neutrophil adhesion, whereas VCAM-1 is a marker of CNS vascular inflammation, suggesting that VLA-4-VCAM-1 interactions may also control neutrophil adhesion during CNS inflammatory diseases." (PMID 36034148, 2022). "Additionally, IL-16, TNF-β and VCAM-1 were also significantly higher in MSM-SN when directly compared to non-MSM-SN indicating GI inflammation, while exacerbated by HIV infection, is elevated in seronegative MSM." (PMID 36605218, 2022). "IL-18 also increases the expression of vascular cell adhesion molecule 1 (VCAM-1) and intercellular adhesion molecule 1 (ICAM-1) in endothelial cells and cardiomyocytes, thus increasing leukocyte recruitment into the injured myocardium and amplifying cardiac inflammation." (PMID 34707513, 2021). "Furthermore, similar to the effects of the miR-146a mimic, IRAK-1 siRNA significantly inhibited the expression of HG-stimulated VCAM-1/ICAM-1 gene expression and THP-1 adhesion to HAECs, indicating that HG-induced endothelial inflammation was mediated partially through IRAK-1." (PMID 28824448, 2017).